TRAJ9 (T cell receptor alpha joining 9)
Gene: T-cell receptor joining (J) gene on chromosome 14 (22,535,554 to 22,535,614, forward strand). Ensembl gene ENSG00000211880.
Diseases named in the same sentence as TRAJ9 in open-access papers:
TRAJ9 is named in the same sentence as 1 disease in open-access papers, as found by Europe PMC text mining. Sharing a sentence is not in itself a finding about the gene and the disease. The quoted sentences say what the papers report.
Legionella infection (1 paper, 2019). "Indeed, after sequencing 111 WT thymic MAIT cell clones ex vivo, we found two that expressed TRAJ9, and another atypical TCR-α sequence was detected in the in vivo-expanded MAIT cells from WT mice following Legionella infection." (PMID 31113973, 2019).